BAX (BCL2 associated X, apoptosis regulator)
Diseases named in the same sentence as BAX in open-access papers (continued):
Sharing a sentence is not in itself a finding about the gene and the disease.
pulmonary fibrosis (6 papers, 2024 to 2025). Chronic progressive interstitial lung disorder characterized by the replacement of the lung tissue by connective tissue, leading to progressive dyspnea, respiratory failure, or right heart failure. "We found that existence of apoptosis resistance in senescent myofibroblasts in pulmonary fibrosis is dependent on “mitochondrial priming”, which may be caused by the simultaneous high expression of BAX and antiapoptotic proteins (BCL‐XL and BCL‐2)." (PMID 38831635, 2024). "BTSA1 protects mice from BLM‐induced pulmonary fibrosis by selectively eliminating senescent myofibroblasts via direct activation of BAX, and can be used as a novel senolytic drug for IPF for reversing established fibrosis." (PMID 38831635, 2024). "For instance, Metformin reverses established pulmonary fibrosis by promoting the apoptosis of myofibroblasts, and BTSA1 induces apoptosis in senescent myofibroblasts via targeted activation of BAX." (PMID 41301772, 2025). "Indeed, it was reported that BAX and CAS-3 increased, and BCL-2 decreased in idiopathic pulmonary fibrosis patients." (PMID 40422811, 2025). "Some researchers have targeted BAX to develop short peptide inhibitors, which significantly improve the progression of type I diabetes or pulmonary fibrosis, but research on BAX/BAK inhibitors for IR has not yet been conducted." (PMID 41514922, 2025). "The BAX activator BTSA1 promotes apoptosis in senescent cells and decelerates pulmonary fibrosis progression, offering a novel senescence clearance strategy for treating pulmonary fibrosis via the promotion of apoptosis in senescent cells." (PMID 40606472, 2025). "We found that α‐SMA+ (red) p21+(pink) senescent myofibroblasts expressed high levels of BAX (green) in lung fibrosis tissue, but BAX6A7 (green) was almost absent in α‐SMA+(red) p21+(pink) senescent myofibroblasts." (PMID 38831635, 2024). "Furthermore, therapeutic activation of BAX with BTSA1 effectively reduced the number of senescent myofibroblasts in the lung tissue and alleviated both reversible and irreversible pulmonary fibrosis." (PMID 38831635, 2024). "Activation of BAX with BTSA1 could selectively eliminated senescent myofibroblasts in vitro and in vivo by converting minority MOMP to complete MOMP to promote apoptosis, thereby alleviating pulmonary fibrosis and blocking the continuous progression of pulmonary fibrosis in vivo." (PMID 38831635, 2024).
skin cancer (6 papers, 2016 to 2025). "Further, it was found that several apoptotic genes including BAX, BAD were upregulated and survival genes such as Bcl-XL was down regulated in A375 skin cancer cell lines." (PMID 28330284, 2016). "Although BAD has not been previously implicated in skin cancers, loss or downregulation of other proapoptotic members of the BCL-2 family, i.e., BAX and PUMA, has been shown to promote the development of BCC, SCC, and cutaneous melanoma." (PMID 34900699, 2021).
triple-negative breast carcinoma (6 papers, 2020 to 2026). An invasive breast carcinoma which is negative for expression of estrogen receptor (ER), progesterone receptor (PR), and human epidermal growth factor receptor 2 (HER2). "Among them, only three circRNAs, namely circ-BAX-6c, circ-BAX-18 and circ-BAX-74, are expressed in all studied triple-negative breast cancer (BrCa) cell lines and in the normal one; moreover, circ-BAX-18 is the only one comprising a novel microexon with canonical splice sites." (PMID 42196148, 2026). "For example, UMI-77 can antagonize MCL1 function by blocking the heterodimerization of MCL1/BAX and MCL1/BAK and exhibits tumor inhibitory activity in a triple-negative breast cancer cell xenograft mouse model." (PMID 34156978, 2021).
acute promyelocytic leukemia (5 papers, 2017 to 2024). An aggressive form of acute myeloid leukemia (AML), characterized by arrest of leukocyte differentiation at the promyelocyte stage, due to a specific chromosomal translocation t(15;17) in myeloid cells. "The expression of miR-766-3p in acute promyelocytic leukemia cells was elevated, while that of BAX, which is a pro-apoptotic protein, was suppressed." (PMID 33302347, 2020). "In acute promyelocytic leukemia cells, the expression of miR-766-3p was elevated, while that of BAX, a pro-apoptotic protein, was suppressed." (PMID 30769772, 2019). "In acute promyelocytic leukemia cells, miR-766 was reported to be down-regulated following arsenic trioxide (As2O3) treatment, resulting in elevation of the miR-766 target BAX and enhanced cell apoptosis." (PMID 28430625, 2017). "In contrast to these studies of NE-regulated suppression of cancer, ELANE is expressed in promyelocytic leukemia (PML) and sustains PML by inhibiting apoptosis via degradation of BAX a pro-apoptotic protein and upregulation of Bcl-2, an apoptosis inhibitor." (PMID 39684750, 2024).
allergic asthma (5 papers, 2013 to 2025). A asthma with a basis in a pathological type I hypersensitivity reaction. "The present MR results suggested the presence of associations between the risk of allergic asthma and BAX, CASP3, CCND1, ICAM1, PEBP1, RAF1, and ERBB2 expression." (PMID 39769348, 2024). "Based on the inverse variance weighted method, the MR analysis provided evidence of associations between allergic asthma and BAX, CASP3, CCND1, ERBB2, ICAM1, PEBP1, and RAF1 in the blood." (PMID 39769348, 2024). "We demonstrated that PIN1 isomerization modulates the pro-apoptotic activity of BAX and the mRNA binding ability of AUF1 thereby influencing immune cell death and cytokine production associated with allergic asthma." (PMID 23675491, 2013). "According to these analyses, IL-1R2, BAX, and TGFB1 were of particular interest due their “High” relationship level with allergic asthma and “Moderate” or weaker relationship value with allergy or nonallergic asthma." (PMID 33936056, 2021). "For allergic asthma, 17 proteins reached a “high” relationship level, one of which (BAX) was not an effector of the disease." (PMID 33936056, 2021).
Burkitt lymphoma (5 papers, 2017 to 2023). A rare form of malignant mature B-cell non-Hodgkin lymphoma. "We recently reported a class B block in a patient with relapsed Burkitt lymphoma, where a mutation in BAX resulted in no production of BAX protein." (PMID 33670870, 2021). "BAX/BAK complex was already reported in other apoptotic responses, as in HeLa cells treated with TNF-α and in Burkitt’s lymphoma cells upon verotoxin-1 treatment." (PMID 32371863, 2020). "Together, these data demonstrate that CHK1 is an essential survival factor for Burkitt lymphoma and pre-B ALL cells and that CHK1 inhibition activates BCL2-regulated and BAX/BAK-dependent apoptosis in these cells." (PMID 29167438, 2017). "To this end we performed proliferation assays with apoptosis-resistant BCL2 overexpressing MYC-transgenic mouse B cells, pre-B ALL cells lacking BAX/BAK, as well as BCL2 overexpressing Burkitt lymphoma cell lines." (PMID 29167438, 2017).
cardiac hypertrophy (5 papers, 2020 to 2025). "Under the pathological state of cardiac hypertrophy, the binding of MANF to BAX can decrease BAX mitochondrial membrane translocation and cytochrome c release to cytoplasm, eventually relieving caspase‐dependent cardiomyocyte apoptosis." (PMID 40739335, 2025). "The expression levels of autophagy-related proteins (ATG7 and LC3A/B) were significantly reduced in aged WT and Y-Sesn2 KO hearts during cardiac hypertrophy, while levels of apoptosis-related proteins (BCL2 and BAX) increased." (PMID 32863202, 2020).
colorectal adenocarcinoma (5 papers, 2017 to 2024). The most common type of colorectal carcinoma. "Recently, Lactobacillus was shown to induce apoptosis of the human colorectal adenocarcinoma cell line HT29 by enhancing pro-apoptotic BAX protein expression and decreasing anti-apoptotic BCL-2 protein expression, leading to the inhibition of cell growth." (PMID 28632155, 2017). "They examined the protein expression level of BAX in normal colorectal mucosa, as well as in primary colorectal adenocarcinomas from early to advanced stages, including cases with metastases to regional lymph nodes." (PMID 28035578, 2017). "In addition to its radiosensitizing effects, NSAIDs have been shown to increase chemosensitivity in colorectal adenocarcinoma cells through an upregulation of the pro-apoptotic protein BAX." (PMID 38229111, 2024).
colorectal tumors (5 papers, 2010 to 2024). "For instance, concerning pro-apoptotic genes, frameshift mutations in the ORF of the BAX gene are reported in >50% of colorectal tumours of the micro-satellite mutator phenotype." (PMID 20221256, 2010). "Our data confirm that MSI can be found very early in the evolution of a colorectal tumor with MSI, we propose that not all sequence alterations are equivalent, and that mutations in the coding microsatellites of TGFβRII and BAX mediate progression from early to late stage CRC with MSI." (PMID 20565851, 2010).
dementia (5 papers, 2022 to 2025). Loss of intellectual abilities interfering with an individual's social and occupational functions. "RVT and mRVT treatment at doses of 5 and 10 mg/kg significantly stimulated Bcl2 and suppressed BAX expression in the cortex and hippocampus of dementia animals." (PMID 39684486, 2024). "The significant increase in the Bcl2/BAX ratio after treatment with the micellar resveratrol (10 mg/kg) indicated an anti-apoptotic effect in the experimental dementia model, suggesting that the micelles could improve resveratrol’s bioavailability." (PMID 39684486, 2024). "Furthermore, micellar resveratrol increased the cAMP-response element-binding protein expression in the cortex and hippocampus of rats as well as the Bcl2/BAX ratio, which indicated an anti-apoptotic effect in the experimental dementia model." (PMID 39684486, 2024). "These assumptions agree with our molecular data showing increased PERK, XBP1, and CHOP expression levels in MCI patients and enhanced ATF6 and BAX in DAT patients, suggesting a pronounced RER stress at the onset of dementia, potentially followed by apoptosis at later stages of the disease." (PMID 37175616, 2023).
head and neck squamous cell carcinoma (5 papers, 2013 to 2025). A squamous cell carcinoma that arises from any of the following anatomic sites: lip and oral cavity, nasal cavity, paranasal sinuses, pharynx, larynx, and salivary glands. "A network involving co-activation of NFκB and STAT3, their compensation for each other, influence on BAX/BCL-XL expression and cell survival has been described in head and neck squamous cell carcinomas." (PMID 24170218, 2013).
Huntington disease (5 papers, 2014 to 2024). Huntington disease (HD) is a rare neurodegenerative disorder of the central nervous system characterized by unwanted choreatic movements, behavioral and psychiatric disturbances and dementia. "Additionally, the maximum expression of BAX in the brain was seen in grade 2 and 3 Huntington’s disease (HD) brains, as described in previous studies." (PMID 37760929, 2023).
nasopharyngeal carcinoma (5 papers, 2019 to 2024). A carcinoma arising from the nasopharyngeal epithelium. "Therefore, in our present study, efforts were made to explore the correlation and effect of BAX -248 G>A and BCL2 -938 C>A SNPs on nasopharyngeal carcinoma (NPC) patients’ survival." (PMID 33906310, 2021). "In addition, exosomes from chronic myeloid leukemia and nasopharyngeal carcinoma tumors were used to promote proliferation of lymphocytes and other cells by increasing BCL-w, BCL-xl, and survivin, and a reduction of the pro-apoptotic molecules BAD, BAX and PUMA." (PMID 31426278, 2019).
retinal degeneration (5 papers, 2014 to 2025). Degeneration of the retina. "The relative mRNA expression of the apoptosis-related genes BAX, BCL2, CASP3, CASP8, and CASP9 was analyzed to study the events associated with the apoptosis process during spontaneous retinal degeneration." (PMID 35221932, 2022). "Recently, increased BAX activation was suggested to be connected to retinal degeneration in rd1, Rho KO, and P23H mice." (PMID 25392995, 2014).
rheumatoid arthritis (5 papers, 2017 to 2024). A chronic, systemic autoimmune disorder characterized by inflammation in the synovial membranes and articular surfaces. "Recent studies by Wang and Peng reported the role of GAS5 in hypoxic-ischemic brain damage and rheumatoid arthritis progression via the miR-128-3p/BAX axis and miR-128-3p/HDAC4 axis." (PMID 36672566, 2022). "The later study reported the mechanistic impact of rs941576 in rheumatoid arthritis; the AA genotype carriers exhibited a significantly decreased serum MEG3 expression and BAX levels and increased hypoxia-inducible factor-1α and vascular endothelial growth factor levels." (PMID 38704452, 2024).
squamous cell carcinoma (5 papers, 2017 to 2025). A carcinoma arising from squamous epithelial cells. "Proapoptotic BAX protein dysregulation also correlates with the progression of cancer and the development of chemoresistance on squamous cell carcinoma of the oral cavity." (PMID 36354566, 2022). "It has also increased the level of BAX/BAK, which is responsible for the increase in apoptosis and necrosis in A431 and NHEK cells of epidermoid carcinoma." (PMID 39246660, 2024). "It has also been reported to boost the activity of apoptotic molecules and BAX, which activates the caspase system of apoptosis in 6 -week-old SINCAR mice with squamous cell carcinoma." (PMID 39246660, 2024). "In squamous cell carcinoma cells, knockdown of GADD45A inhibits apoptosis, with the reduction of BAX gene expression and induction of BCL-2 gene expression." (PMID 33406670, 2021).
ulcerative colitis (5 papers, 2019 to 2025). An inflammatory bowel disease involving the mucosal surface of the large intestine and rectum. "Matching with this, the anti-apoptotic effect of SA was assessed against ulcerative colitis, as it inhibited BAX and stimulated anti-apoptotic Bcl-2 expression." (PMID 40426893, 2025). "The results showed that cycloastragenol treatment improved the induced morphological changes, and in ulcerative colitis rats, this compound significantly reduced expression levels of SphK, MIP-1α, BAX, NF-κB, TNF-α, and active caspase-3, associated with BCL2 and miR-143 overexpression." (PMID 41304636, 2025). "Ulcerative colitis rats were treated with 30 mg/kg cycloastragenol, and the gene and protein expression levels of SphK, MIP-1α, B-cell lymphoma 2 (BCL2), BCL2-associated X (BAX), miR-143, NF-κB, tumor necrosis factor (TNF)-α, and active caspase-3 were assessed." (PMID 41304636, 2025). "In this study, we evaluate the expression of the BAX, BCL2, CASP3 and CASP9 genes at the mRNA level in the peripheral blood lymphocytes of patients with ulcerative colitis and Crohn’s disease during the disease process." (PMID 31159239, 2019). "Expression of the genes BAX, BCL2, CASP3 and CASP9 was assessed at the mRNA level in the peripheral blood lymphocytes of patients with ulcerative colitis and Crohn’s disease relative to the healthy subjects." (PMID 31159239, 2019).
acute kidney injury (4 papers, 2022 to 2025). Sudden and sustained deterioration of the kidney function characterized by decreased glomerular filtration rate, increased serum creatinine or oliguria. "In a model of cisplatin-induced acute kidney injury, cisplatin caused mtDNA leakage into the cytoplasm through the mitochondrial outer membrane BAX/BAK pore, activated the cGAS-STING signaling pathway, and resulted in inflammation and acute kidney injury." (PMID 37667279, 2023).
amyotrophic lateral sclerosis (4 papers, 2011 to 2025). Amyotrophic lateral sclerosis (ALS) is a neurodegenerative disease characterized by progressive muscular paralysis reflecting degeneration of motor neurons in the primary motor cortex, corticospinal tracts, brainstem and spinal cord. "The enrichment of KEGG correlated with BAX is the spliceosome, amyotrophic lateral sclerosis and RNA transport (P < 0.05)." (PMID 39074253, 2024). "Similarly, GeneCOCOA also reported false positive associations in the amyotrophic lateral sclerosis (ALS) data set for the genes BCL2 and BAX." (PMID 40163580, 2025).
autoimmune disease (4 papers, 2019 to 2024). A disorder resulting from loss of function or tissue destruction of an organ or multiple organs, arising from humoral or cellular immune responses of the individual to their own tissue constituents. "BAX is a pro-apoptotic gene that may play a critical role in regulating cell death in many different autoimmune diseases." (PMID 38732072, 2024). "BAX is a proapoptotic molecule, member of the BCL-2 family, with a recognized role to control immune tolerance and prevent autoimmune disorders in mice." (PMID 35205739, 2022).
cardiomyopathy (4 papers, 2020 to 2025). A disease of the heart muscle or myocardium proper. "BAX activation has recently been shown to be a rate-limiting step in doxorubicin-induced cardiomyopathy." (PMID 39408900, 2024). "BAX activation has recently been indicated as rate-limiting step in doxorubicin-induced cardiomyopathy." (PMID 32752227, 2020). "Further preclinical and clinical drug studies targeting BAK/BAX for the treatment of cardiomyopathy may have broad prospects." (PMID 41514922, 2025).
cholestasis (4 papers, 2021 to 2025). Impairment of the bile flow caused by obstruction within the liver, or outside the liver in the bile duct system. "Similarly, the levels of TC, TBA, γ-GT, TBIL, the expression of TNF-α, TIMP-1, and the BAX/BCL-2 ratio were significantly increased in cholestasis-induced rats compared with the control rats, and these changes were effectively alleviated following treatment with ZYP." (PMID 34539394, 2021).
depression (4 papers, 2019 to 2025). "Depression and BAX apoptosis signaling are highly correlated." (PMID 35269511, 2022). "While both BAX−/− and MOAP-1−/− mice showed depression-like behavior, they differ in another aspect." (PMID 30003515, 2019). "In addition, the upregulation of BAX and downregulation of BCL2 were observed in the olfactory bulb of a rat depression model." (PMID 35269511, 2022).